GSTM1 (glutathione S-transferase mu 1)
Diseases named in the same sentence as GSTM1 in open-access papers (continued):
Sharing a sentence is not in itself a finding about the gene and the disease.
diabetes (23 papers, 2006 to 2025). "Among six investigated GST polymorphisms, a significant association between GST genotype and susceptibility for development of diabetes mellitus was found for the GSTM1, GSTT1, GSTP1 (rs1138272) and GSTO1 (rs4925) polymorphisms." (PMID 36676788, 2023). "According to the reviewed literature, few studies have been published on the association between GSTT1/GSTM1 polymorphism and susceptibility to diabetes, and there are large divergences among the study results." (PMID 24098457, 2013). "The OR obtained for the GSTM1-null genotype was 3.7, indicating an association between the incidence of diabetes and GSTM1 deletion polymorphism." (PMID 24098457, 2013). "We reported earlier that individuals with diabetes with the null GSTM1 polymorphism have the greatest PM-associated decreases in endothelial dysfunction." (PMID 20525188, 2010). "Here, we extend these findings by showing that individuals with diabetes carrying the null allele for GSTM1 also have the most pronounced changes in IL-6, RBC, total hemoglobin and MCV." (PMID 20525188, 2010). "The GSTM1 null-allele polymorphism is associated with reduced mitochondrial enzyme activity, decreased ability to detoxify compounds, increased level of reactive oxygen species, and increased risk of cancers, diabetes mellitus, and other diseases of aging, primarily among Caucasians." (PMID 24416632, 2013). "For example, genes involved in glutathione metabolism such as Gstm1 were upregulated in macroglia from Akimba mice as well as specifically in Müller cells in our diabetes model, indicating a consistent anti-stress response of the cells in both models." (PMID 38273366, 2024). "Individuals with the GSTM1 null genotype were more prone to develop diabetes in comparison with GSTM1 active carriers (OR = 1.97, 95%CI = 1.14–3.40, p = 0.015)." (PMID 36676788, 2023). "The incidence of ischemic stroke is probably increased by the interaction of GSTT1 and GSTM1 null genotypes with high blood pressure, diabetes and cigarette smoking." (PMID 37240845, 2023). "Glutathione-S-transferase including GSTMI, GSTM1, and GSTP1 are important genes and their association with diabetes has been investigated in two meta-analysis studies." (PMID 26587547, 2015). "Regarding the complications of diabetes, it has been shown that GSTT1 wild allele and GSTT1 wild/GSTM1 null genotype can be considered as risk factors for cardiovascular autonomic neuropathy in Slovak adolescents with T1DM." (PMID 24355557, 2013). "Two studies (one in smokers, and the other in patients with diabetes), reported an association between GSTT1 and GSTM1 null mutations and lower levels of the inflammatory biomarker CRP, itself associated with poor survival." (PMID 24083102, 2013). "Additionally, the combination of null GSTM1 and OGG1, null GSTT1 and OGG1 and GSTM1, GSTT1 and GSTP1 was revealed to be significantly associated with increased risk of diabetes in Turkish population." (PMID 29682485, 2017). "In particular, the association of the most extensively studied deletion (null) polymorphisms in GST mu 1 (GSTM1) and GST theta 1 (GSTT1) genes, which results in a complete lack of corresponding enzymes, has been described to be involved in T2DM development and diabetes-related complications." (PMID 36676788, 2023). "Our study comprises the largest cohort of Black participants in which the association between GSTM1 status and CKD has been explored; the GSTM1 groups were indistinguishable in terms of HIV parameters and relevant comorbidities, such as hypertension and diabetes, and APOL1 renal risk status." (PMID 35967115, 2022). "We found no significant statistical association between GSTM1, GSTT1, and GSTP1 genotypes and the presence of DSPN in patients with diabetes mellitus." (PMID 26435566, 2015).
diabetes (continued). "The statistical analysis of GSTM1 gene deletion in controls (diabetes without retinopathy) (65.5%) and cases (diabetes with retinopathy) (45.6%) group indicates a significant relationship with df = 1, p-value = 0.04, and χ2 = 4.646." (PMID 24355557, 2013). "However, the log-linear analysis revealed that there isn’t a contribution of GSTM1 polymorphism in susceptibility to diabetes (p = 0.578), and moreover, we can conclude that GSTM1- present may not buffer a deficiency caused by GSTT1-deletion, since the risk to T2DM remained high." (PMID 24098457, 2013). "Therefore, in this study GSTM1 and GSTT1 null genotype as one of the genetics factors which may be related to the diabetes and its complications is investigated." (PMID 24355557, 2013).
coronary artery disease (19 papers, 2005 to 2025). "A meta-analysis by Su et al120 found that the GSTM1 null polymorphism is significantly associated with an increased risk of coronary artery disease in both the overall and mixed populations." (PMID 40290119, 2025). "The association of the genetic variants in the genes encoding GSTs, especially GSTM1 cluster, with cardiac problem, such as coronary artery disease, ischemic heart disease or heart failure were described in several GWAS across different populations worldwide." (PMID 37819495, 2023). "A recent meta-analysis suggested that the GSTM1*0/0 genotype associated with an increased risk of ischemic heart disease (OR, 1.38; 95% CI, 1.01 to 1.87)." (PMID 24423050, 2014). "The association of the GSTT1 and GSTM1 null-genotypes with coronary artery disease (CAD) among smokers has been the subject of many investigations, but to our knowledge no such studies have been conducted among Arabs." (PMID 16620396, 2006). "The association of the deletion in GSTT1 and GSTM1 genes with coronary artery disease (CAD) among smokers is controversial." (PMID 16620396, 2006). "Genes belonging to the GST superfamily have been studied in metabolic disorders; for example, GSTA4 has been shown to be downregulated in obese individuals in relation to the inflammatory state associated with obesity, and GSTM1 null-polymorphisms have been linked to coronary heart disease." (PMID 39519120, 2024). "Recently, Wang and co-workers reported that GSTM1 deficiency is associated with the risk of vascular diseases, while they did not observe any interaction between the status of cigarette smoking and GSTM1 deficiency in relation to coronary arterial disease severity." (PMID 16136034, 2005). "The SNPs targeted by our study, GSTM1 and GSTT1, are susceptible to deletion and complete loss of enzymatic activity and are related to coronary diseases, different types of cancer, and various infections." (PMID 40867808, 2025). "There are meta-analyses demonstrating that GSTM1 null, GSTP1 null and GSTT1 null polymorphisms were significantly associated with an increased risk of coronary artery disease (CAD) in overall population." (PMID 37819495, 2023). "Previous studies in India have demonstrated an association between GSTM1/GSTT1/glutathione S-transferase π1 (GSTP1) polymorphism, coronary heart disease and blood lipid parameters." (PMID 31638212, 2019). "However, among the Indian population of South Africa, a correlation between the GSTM1-null genotype and the A105 allele of GSTP1 and ischemic heart disease was found." (PMID 37819495, 2023). "Their findings confirm the results of the meta-analysis (involving more than 47,500 subjects) in which overall lack of association between GSTM1 genotypes and coronary heart diseases was shown." (PMID 37819495, 2023). "The GSTM1 deficiency is linked to higher susceptibility to CVD as individuals with GSTM1-null genotype were shown to have significantly increased risk for developing resistant hypertension, coronary artery disease/atherosclerosis, and stroke." (PMID 33574979, 2021). "In coronary artery disease (CAD) as the most common etiology of heart failure in industrialized countries, genetic epidemiologic studies mostly investigated the association of common GSTA1, GSTM1, GSTT1, and GSTP1 polymorphisms with disease risk." (PMID 31275451, 2019). "On the other hand, studies on the Taiwanese population did not reveal that the GSTM1, GSTT1, GSTP1 and GSTA1 polymorphisms were associated with ischemic heart disease." (PMID 37819495, 2023). "The possible reason may be that GSTM1 null genotype could influence the susceptibility to non-cancer diseases, such as COPD, alcoholic liver disease, and coronary heart disease, so its genotype frequency possibly differed between the hospital-based and population-based controls." (PMID 23189206, 2012).
hepatocellular carcinoma (18 papers, 2009 to 2024). A malignant tumor that arises from hepatocytes. "GSTM1 is also a risk factor of relapse in childhood acute lymphoblastic leukemia and hepatocellular carcinoma." (PMID 32539715, 2020). "Overall, two studies have identified the deletion of GSTM1 and GSTT1 haplotypes as risk factors for aflatoxin-associated hepatocellular carcinoma in Africa." (PMID 33659210, 2020). "The combination of GSTM1 null and GSTP1 Val was significantly associated with an increased risk of lung cancer and hepatocellular carcinoma." (PMID 24517907, 2014). "This is the most comprehensive meta-analysis that examined the GSTM1, GSTT1 null polymorphism and the relationship to susceptibility for hepatocellular carcinoma." (PMID 23185284, 2012). "Our results demonstrated that the GSTM1 and GSTT1 null polymorphism is a risk factor for developing hepatocellular carcinoma." (PMID 23185284, 2012). "Moreover, the term “Hepatocellular carcinoma” is enriched with FZD8, ribosomal protein S6 kinase alpha-6 (PRSAKA6), TGFB3 and GSTM1." (PMID 34150612, 2021). "GSTM1 functions as a tumor suppressor gene in hepatocellular carcinoma; however, the prognostic value was not reported." (PMID 32539715, 2020).
Hypertension (18 papers, 2006 to 2025). The presence of chronic increased pressure in the systemic arterial system. "Clinical studies have suggested a potential association between the GSTM1 null polymorphism and increased susceptibility to cardiovascular diseases, including hypertension, atherosclerosis, and heart failure." (PMID 40448227, 2025). "Studies conducted on the North Indian population have shown that GSTT1 null genotype and GSTM1 positive genotype are associated with the development of essential hypertension in the subject with impaired lipid profile." (PMID 37819495, 2023). "While in humans, loss of one or both copies GSTM1 is associated hypertension in the elderly, as well as with kidney and heart failure." (PMID 35614104, 2022). "In particular, the GSTM1 null genotype has been associated with an increased risk of blood pressure-related disorders such as preeclampsia and hypertension." (PMID 36139130, 2022). "Several cases-controls studies have reported that GSTT1 and/or GSTM1 null genotype were associated to the risk of developing hypertension in some populations, but rather the results are still controversial." (PMID 32188413, 2020). "Concerning GSTM1, the previous meta-analysis implied that GSTM1 null genotype was positively associated with the risk of hypertension (OR = 1.22; 95% CI: 1.08, 1.39; P = 0.002)." (PMID 25742618, 2015). "There are 14 studies with 2773 hypertension cases and 3189 controls concerning GSTM1 polymorphism and 13 studies with 2497 hypertension cases and 3078 controls concerning GSTT1 polymorphism." (PMID 25742618, 2015). "It seems that GSTT1 and GSTM1 polymorphisms cannot influence the risk of hypertension in all studies." (PMID 25742618, 2015). "Data from the African American Study of Kidney Disease and Hypertension revealed an association between GSTM1 inactive genotypes and accelerated progression of CKD in a cohort of 692 Black Americans with hypertensive kidney disease, with worse progression in APOL1 high-risk genotypes." (PMID 35967115, 2022). "The present study aimed to test the hypothesis that the loss of activity of the enzyme due to a deletion polymorphism in the GSTT1 and GSTM1 may affect the risk of developing hypertension." (PMID 23105984, 2012). "Investigate the association between GSTT1 and GSTM1 polymorphism and hypertension." (PMID 23105984, 2012). "GSTT1 & GSTM1 polymorphism can be considered a risk factor for hypertension." (PMID 23105984, 2012). "Noteworthy is the fact that the subjects with hypertension and the GSTM1-null genotype had lower triglyceride concentration than the subjects with the GSTM1-positive genotype." (PMID 37819495, 2023). "Experimentally, renal expression of glutathione-S-transferase μ-type 1 (GSTM1) is reduced in hypertensive rats, with transgenic overexpression reducing hypertension in the stroke-prone spontaneously hypertensive (SHRSP) rat59." (PMID 35614104, 2022). "The present study investigated the factors associated with blood pressure control in patients with essential hypertension, especially the role of GSTT1 and GSTM1 genes polymorphisms." (PMID 34193266, 2021). "Considering the genetic aspects, we investigated the influence of variants of the GSTM1 and GSTT1 genes on the control of essential hypertension." (PMID 34193266, 2021). "In this study, we aimed to characterize firstly null variants of GSTM1 and GSTT1 in Burkina Faso and secondly to evaluate the association between them and the risk of developing essential hypertension." (PMID 32188413, 2020). "Some studies have shown that GSTM1 and/or GSTT1 were associated with essential hypertension risk, other authors have shown that only the double deletion GSTM1/GSTT1 was associated with essential hypertension risk, and other failed to confirm any association." (PMID 32188413, 2020). "In the present study, we characterize the null genotypes of GSTM1 and GSTT1 in order to investigate the association between them and the risk of developing essential hypertension." (PMID 32188413, 2020).
Hypertension (continued). "The present study aimed to characterize firstly the null genotype of GSTM1 and GSTT1 genes in Burkina Faso and secondly to analyzes a possible association between them and the risk of developing essential hypertension." (PMID 32188413, 2020). "In the AASK study, a randomized trial comparing different antihypertensive medications and levels of blood pressure control in blacks with CKD attributed to hypertension, 692 participants had GSTM1 genotyping completed." (PMID 31555322, 2019). "In a Turkish population, GSTT1 and GSTM1 nullgenotypes, together with hypertension, were seen to play a significant role in thepathogenesis of ischemic stroke (Türkanogluet al., 2010)." (PMID 29658969, 2018). "The meta-analysis resulted in a statistically non-significant association between both the null genotypes of GSTM1 and GSTT1 and hypertension (OR = 1.23, 95% CI: 0.49, 3.10)." (PMID 25742618, 2015). "Some studies have recently focused on the association between glutathione S-transferase M1 (GSTM1) and glutathione S-transferase T1 (GSTT1) null polymorphisms and hypertension; however, results have been inconsistent." (PMID 25742618, 2015). "In order to drive a more precise estimation, the present systematic review and meta-analysis is performed to investigate the relationship between the GSTM1 and GSTT1 null polymorphisms and hypertension." (PMID 25742618, 2015). "The present meta-analysis examined the effect of GSTM1 and GSTT1 null polymorphisms on the risk of hypertension." (PMID 25742618, 2015). "Further studies with unbiased-matched homogeneous patients and well matched controls are required to examine associations between the GSTM1 and GSTT1 polymorphisms and hypertension risk." (PMID 25742618, 2015). "Regarding the GSTM1 null/present genotype, 14 case—control studies were eligible (2773 hypertension cases and 3189 controls)." (PMID 25742618, 2015). "In this study, we perform a carefully designed and complete meta-analysis to define the effect of GSTM1 and GSTT1 null polymorphisms on the risk for hypertension." (PMID 25742618, 2015). "In our own studies in the SHRSP we have identified the glutathione S-transferase mu type 1 gene (Gstm1) as a positional candidate for hypertension in the SHRSP." (PMID 20035862, 2010). "We then entered the GSTM1 genotype (variable) into a stepwise multiple logistic regression with CAD risk factors, resulting in the retention of the genotype, hypertension, elevated cholesterol, obesity, smoking and genotype-smoking interaction." (PMID 16620396, 2006). "However large-scale study will be necessary to fully comprehend the role of GSTM1 and GSTT1 variant in the development of essential hypertension." (PMID 32188413, 2020). "Previous studies showed that a homozygous deletion, or null genotype, at either the GSTM1 locus or the GSTT1 locus resulted in enzyme function loss, which was hypothesized to be related to risk of hypertension." (PMID 25742618, 2015). "Summary of meta-analysis of studies examining GSTM1 and GSTT1 polymorphisms and hypertension risk." (PMID 25742618, 2015). "Furthermore, by conserved genome analysis, a data set of 73 candidate genes for hypertension, including Cd36 and Gstm1, have been identified that merit translational studies in human populations." (PMID 20035862, 2010). "The human orthologues of Gstm1 are therefore promising candidate genes for essential hypertension." (PMID 20035862, 2010). "We previously investigated the link between Glutathione S-transferases Mu1 (GSTM1) and theta 1 (GSTT1) variants and the risk of developing essential hypertension and found that GSTT1-null genotype was associated with the risk of developing hypertension in Burkina Faso." (PMID 34193266, 2021). "The pooled estimator for GSTM1 null suggested that it might show a similarly small increased risk for hypertension, although the effect was not statistically significant (OR = 1.16, 95% CI: 0.96, 1.40; I2 = 59.8%, P = 0.002)." (PMID 25742618, 2015).
Hypertension (continued). "This allows us to infer that the absence of GSTM1 and GSTT1 may contribute to type 2 diabetes-related complications, such as dyslipidemia (GSTT1), glycemic de-compensation and hypertension (GSTM1)." (PMID 24098457, 2013). "As MASLD and hypertension are common co-morbidities, a study regarding differences in GSTM1 and GSTO1 protein expression in normotensive and hypertensive rats was performed which showed significant GSTO1 downregulation and no change in GSTM1 levels in hypertensive rats." (PMID 39443317, 2025).